EGFR (epidermal growth factor receptor)
Diseases named in the same sentence as EGFR in open-access papers (continued):
Sharing a sentence is not in itself a finding about the gene and the disease.
head and neck squamous cell carcinoma (continued). "Epidermal growth factor receptor (EGFR) has been characterized as a critical factor in the development and progression of multiple solid tumors, including head and neck squamous cell carcinoma (HNSCC)." (PMID 23963114, 2013). "The aim of this study is to understand the mechanism of EGFR overexpression in head and neck squamous cell carcinoma (HNSCC)." (PMID 23675485, 2013). "Previous reports suggest that EGFR is over-expressed in ∼90% of head and neck squamous cell carcinoma (HNSCC) and EGFR over-expression has been linked to the presence of EGFRvIII at other cancer sites." (PMID 22359620, 2012). "EGFR overexpression is a frequent occurrence in many cancers that corresponds to poor clinical outcome, including breast and head and neck squamous cell carcinoma (HNSCC)." (PMID 22952966, 2012). "This review highlights three RTK signaling pathways involved in head and neck squamous cell carcinoma; EGFR, the type 1 insulin-like growth factor receptor (IGF-1R) and the hepatocyte growth factor (HGF) receptor (Met)." (PMID 21776391, 2011). "The epidermal growth factor receptor (EGFR) is one of the major targets under intensive investigation since it has been found to be overexpressed in head and neck squamous cell carcinoma." (PMID 21917153, 2011). "A previous study of head and neck squamous cell carcinoma indicated an increase in SP cells by activation of HER1/EGFR signalling." (PMID 20145614, 2010). "The only randomized phase III trial published to date examining radiation versus radiation plus an EGFR inhibitor used cetuximab in locally advanced head and neck squamous cell carcinoma." (PMID 19657384, 2009). "For instance, EGFR amplification as determined by FISH has been shown to be independently associated with poor survival in vulvar cancer and in head and neck squamous cell carcinomas." (PMID 19513073, 2009). "High levels of EGFR expression are correlated with poor prognosis and resistance to radiation therapy in a variety of cancers, mostly in squamous-cell carcinoma of the head and neck (SCCHN)." (PMID 16722544, 2006). "Numerous studies reported a correlation between over-expression of the epidermal growth factor receptor (EGFR, c-erbB1) and poor prognosis in head and neck squamous cell carcinomas." (PMID 17029632, 2006). "Overexpression of EGFR predicts a poor prognosis in many cancers, particularly in head and neck squamous cell carcinomas, and consequently EGFR is a prime target for anticancer therapy." (PMID 11986789, 2002). "To date, 4 anti‐EGFR monoclonal antibodies named cetuximab, panitumumab, necitumumab, and nimotuzumab have been approved for clinical use, normally used in the head and neck squamous cell carcinoma (HNSCC), metastatic colorectal cancer (mCRC), and other solid tumors." (PMID 40859900, 2025). "Additionally, 3D patient-derived head and neck squamous cell carcinoma spheroids showed differential protein expression profiles of epidermal growth factor receptor (EGFR), EMT, and stemness markers." (PMID 40227664, 2025). "In another approach, EGFR-targeting exosomes have been generated by displaying anti-EGFR nanobodies or peptides on their surface, enabling selective delivery to EGFR-overexpressing head and neck squamous cell carcinoma cells." (PMID 41154440, 2025). "EGFR is frequently overexpressed and activated in Head and Neck Squamous Cell Carcinoma (HNSCC)." (PMID 39130636, 2024). "Moreover, NIR-PIT targeting the epidermal growth factor receptor (EGFR) using a cetuximab-IR700 conjugate was approved in Japan in September 2020 for the treatment of recurrent head and neck squamous cell carcinoma." (PMID 39061197, 2024).
head and neck squamous cell carcinoma (continued). "However, Epidermal Growth Factor Receptor (EGFR) has been studied extensively, and it is known that it is upregulated in most (up to 90%) head and neck squamous cell carcinoma patients and is associated with a poor prognosis." (PMID 36833361, 2023). "EGFR is overexpressed in approximately 50 to 90% of head and neck squamous cell carcinoma cases." (PMID 35653344, 2022). "Given that HDAC inhibitors are currently being tested in clinical trials for head and neck squamous cell carcinomas and the demonstrated synergism when combined with EGFR inhibitors, CHD4 could constitute a clinically relevant response biomarker." (PMID 36362284, 2022). "In their phase I/II trial, this group showed clinical responses in the treatment of patients with epidermal growth factor receptor (EGFR or HER1)‐expressing head and neck squamous cell carcinoma using a combination of s.c. administered IL‐12 and the anti‐EGFR monoclonal antibody cetuximab." (PMID 35790025, 2022). "Besides, D1 (A12) restrains the progression of head and neck squamous cell carcinoma by reducing HERS-transactivation induced by retarded hormone and even has therapeutic prospects for EGFR TKI-resistant head and neck squamous cell carcinoma." (PMID 36466812, 2022). "Furthermore, the clinical use of EGFR-targeted NIR-PIT progressed into clinical trials of patients with head and neck squamous cell carcinoma (HNSCC)." (PMID 35740662, 2022). "Conclusively, our results suggest that neither EGFRvIII nor EGFR R521K variants are directly resulting cetuximab resistance in Head and neck squamous cell carcinoma patients." (PMID 35626010, 2022). "However, results are controversial since IL-1α alone was also reported to increase and predict the efficacy of anti-EGFR in head and neck squamous cell carcinoma." (PMID 36712972, 2022). "Finally, in the KEYNOTE-048 clinical trial, Pembrolizumab (immunotherapy that targets PD-L1) with chemotherapy improved overall survival versus Cetuximab (EGFR targeted therapy) with chemotherapy in patients with head and neck squamous cell carcinoma." (PMID 36230688, 2022). "The EGFR-targeting antibody cetuximab (CTX) combined with radiotherapy is the only targeted therapy that has been proven effective for the treatment of locally advanced head and neck squamous cell carcinoma (LA-HNSCC)." (PMID 34207120, 2021). "However, a high expression ratio between Gene 33 and EGFR is positively associated with resistance to the EGFR inhibitor erlotinib by a panel of cancer cells, including human NSCLC cells, bladder cancer cells, and head and neck squamous cell carcinoma cells." (PMID 34206547, 2021). "The majority of patients with head and neck squamous cell carcinoma treated with a cetuximab-based therapy have been shown, EGFR variation could be a useful biomarker for less skin toxicity and poor prognosis." (PMID 33680380, 2020). "Despite the high prevalence of epidermal growth factor receptor (EGFR) overexpression in head and neck squamous cell carcinomas (HNSCCs), incorporation of the EGFR inhibitor cetuximab into the clinical management of HNSCC has not led to significant changes in long-term survival outcomes." (PMID 30890189, 2019). "The EGFR pathway plays a critical role in head and neck squamous cell carcinoma (HNSCC)." (PMID 31462653, 2019). "We found a significant association of EGFR expression with tumor stage and disease-free survival, which are the most important prognostic factors in head and neck squamous cell carcinoma; therefore, EGFR expression can be used as a prognostic biomarker in head and neck squamous cell carcinoma." (PMID 29954411, 2018).
head and neck squamous cell carcinoma (continued). "Anti-CD27 may also enhance the efficacy of other ADCP-dependent tumour-targeting mAbs in other cancers, such as anti-EGFR in head and neck squamous cell carcinoma and anti-GD2 in neuroblastoma." (PMID 30413184, 2018). "In head and neck squamous cell carcinoma, the epidermal growth factor receptor (EGFR) is commonly overexpressed and investigation of agents that block this receptor indicate a limited response when used alone but an ability to enhance the actions of other drugs." (PMID 29568372, 2018). "We found a significant association of EGFR expression with tumor stage and disease-free survivals, which are the most important prognostic factors in head and neck squamous cell carcinoma; therefore, EGFR expression can help as a prognostic biomarker in head and neck squamous cell carcinoma." (PMID 29954411, 2018). "In head and neck squamous cell carcinomas, RAS mutations may confer resistance to therapies using EGFR tyrosine kinase inhibitors or anti-EGFR antibodies in experimental and clinical studies." (PMID 29682203, 2018). "There has been a debate over whether the addition of anti-epidermal growth factor receptor (EGFR) agents to the conventional treatments has beneficial effects in patients with head and neck squamous cell carcinoma (HNSCC)." (PMID 29254252, 2017). "Some studies imply that EGFRvIII may be responsible for the poor response to the monoclonal EGFR-antibody Cetuximab, used therapeutically in head and neck squamous cell carcinoma (HNSCC)." (PMID 28427242, 2017). "ADCC is a well-established effector pathway that contributes to the therapeutic activity of monoclonal antibodies (mAbs) such as cetuximab, an epidermal growth factor receptor (EGFR)-specific mAb approved for treatment of patients with squamous cell carcinoma of the head and neck (SCCHN)." (PMID 26928328, 2016). "EGFR is an extensively studied biomarker in head and neck squamous cell carcinoma (HNSCC)." (PMID 27556186, 2016). "Furthermore, combined inhibition of PLCγ1 and c-Src abrogates EGFR-mediated head and neck squamous cell carcinoma invasion." (PMID 26811493, 2016). "Similarly, NIR dye labeled EGFR antibody Cetuximab was used to visualize EGFR expression in head and neck squamous cell carcinomas." (PMID 26848870, 2016). "Therefore, the role of nimotuzumab in the prevention of angiogenesis in addition to EGFR targeting would be an added advantage in controlling the invasion of head and neck squamous cell carcinoma." (PMID 25918252, 2015). "Overexpression of EGFR has been observed in up to 90% of head and neck squamous cell carcinomas." (PMID 25918252, 2015). "A Cy5.5-labeled anti-EGFR antibody, cetuximab, was used to image head and neck squamous cell carcinoma xenografts in vivo, and the results demonstrated the capability of a fluorescently labeled anti-EGFR antibody to be utilized for detecting human tumors in a surgical setting." (PMID 25663888, 2015). "Moreover, EGCG has been proved to have inhibitory properties on cell proliferation of breast and head and neck squamous cell carcinomas (HNSCC) by suppressing the activity of EGFR, signal transducer and activator of transcription 3 (STAT3), Akt and c-fos." (PMID 25918934, 2015). "In this regard, the anti-EGFR antibody cetuximab has been approved alone or in combination with: (a) chemotherapy for treatment of colorectal and head and neck squamous cell carcinoma and (b) with external radiotherapy for treatment of head and neck squamous cell carcinoma." (PMID 24603603, 2014). "Cetuximab (Erbitux) is an anti-EGFR mAb which is approved for the treatment of squamous cell carcinoma of the head and neck (SCCHN) and K-Ras mutation negative, EGFR positive, mCRC." (PMID 24738036, 2014). "EGFR-targeted therapy is an attractive option for head and neck squamous cell carcinoma patients." (PMID 25240937, 2014).
head and neck squamous cell carcinoma (continued). "The anti-EGFR antibody cetuximab used in combination with radiotherapy or chemotherapy exhibited a significant clinical benefit when used against head and neck squamous cell carcinoma, leading to an ongoing intensive clinical trial using cetuximab for the treatment of ESCC." (PMID 23426935, 2013). "The epidermal growth factor receptor (EGFR) represents a target in cancer therapy, in particular for head and neck squamous cell carcinoma (HNSCC), where EGFR overexpression is associated with poor prognosis." (PMID 41281627, 2026). "In head and neck squamous cell carcinoma (HNSCC), where EGFR is overexpressed in over 90% of cases, the use of EGFR-TKI has shown promising results." (PMID 39863836, 2025). "One of the most promising molecular treatments for head and neck squamous cell carcinoma HNSCC is targeting the EGFR." (PMID 40296914, 2025). "One example of such modification, Ad5 targets the EGFR, which is overexpressed in many types of head and neck squamous cell carcinoma (HNSCC)." (PMID 40697381, 2025). "Cetuximab-IRdye700DX (Cmab-IR700) conjugate is commonly used in NIR-PIT for head and neck squamous cell carcinoma (HNSCC) because of the frequent overexpression of epidermal growth factor receptor (EGFR) in HNSCC cells." (PMID 40273966, 2025). "The impact of treatment sequence on therapeutic efficacy is emerging as a critical question in head and neck squamous cell carcinoma (HNSCC), where both anti-EGFR therapy and immunotherapy represent major therapeutic advances." (PMID 41205596, 2025). "Epidermal growth factor receptor tyrosine kinase inhibitors (EGFR-TKIs) like gefitinib, erlotinib and lapatinib (EGFR-TKIs) are administered with chemotherapeutic agents to enhance their sensitivity in head and neck squamous cell carcinoma (HNSCC)." (PMID 38529190, 2024). "For example, in the treatment of head and neck squamous cell carcinoma (HNSCC), Cetuximab, which targets the Epidermal Growth Factor Receptor (EGFR), has been shown to enhance the effects of platinum-based chemotherapy." (PMID 39335671, 2024). "The present systematic review evaluated the effectiveness of anti-EGFR therapy in combination with radiotherapy (RT) or with chemoradiation compared with the existing standard of care for the treatment of locally advanced head and neck squamous cell carcinoma (LAHNSCC)." (PMID 38873325, 2024). "In human head and neck squamous cell carcinoma (HNSCC), an approved epidermal growth factor receptor (EGFR) antibody named cetuximab is used for treating the metastatic form of cancer." (PMID 38705513, 2024). "It is worth noting that another phase I clinical trial is underway to evaluate the clinical efficacy of EGFR monoclonal antibody, cetuximab and levatinib in the treatment of patients with head and neck squamous cell carcinoma (HNSCC)." (PMID 39653700, 2024). "More specifically, co-administration of monalizumab and cetuximab, an anti-EGFR antibody, in patients with head and neck squamous cell carcinoma (HNSCC) resulted in the induction of anti-tumor memory." (PMID 39339180, 2024). "Nanobody‐targeted PDT remains therapeutic in tumor head and neck squamous cell carcinoma (HNSCC) organoids with low EGFR expression levels, whereas the corresponding normal organoids did not respond to EGFR‐targeted PDT." (PMID 37693042, 2023). "The conventional first-line treatment in head and neck squamous cell carcinomas (HNSCC) involves the combination of chemotherapy and the anti-EGFR antibody cetuximab." (PMID 37296876, 2023). "Additionally, PIK3CA and/or EGFR amplification and Rictor overexpression in head and neck squamous cell carcinoma and lung squamous cell carcinoma, and the RICTOR amplification detected in our study are associated with the fact that mTOR inhibitors are under investigation in these tumours." (PMID 37949943, 2023). "There is no strong and reliable predictive biomarker in head and neck squamous cell carcinoma (HNSCC) for EGFR inhibitors." (PMID 38110561, 2023).
head and neck squamous cell carcinoma (continued). "As a result, only one molecular therapy has so far been approved for use with RT, namely the anti-epidermal growth factor receptor (EGFR) antibody cetuximab in head and neck squamous cell carcinoma (HNSCC)." (PMID 37041372, 2023). "Mechanistically, it has been shown that HA mediates the formation of a complex including CD44 and the epidermal growth factor receptor (EGFR), which plays major roles in chemoresistance in head and neck squamous cell carcinoma (HNSCC)." (PMID 37958796, 2023). "Patients with head and neck squamous cell carcinoma (HNSCC) benefit from cetuximab treatment which targets the epidermal growth factor receptor (EGFR)." (PMID 35205415, 2022). "Cetuximab (Erbitux®), an anti-EGFR chimeric IgG1 antibody, was used to metastatic colon cancer and head and neck squamous cell carcinoma (HNSCC)." (PMID 35758066, 2022). "EGFR is a prototypical receptor tyrosine kinase that is overexpressed in multiple cancers including head and neck squamous cell carcinoma (HNSCC)." (PMID 35409179, 2022). "We explored the effect of combination of EGFR inhibition with a short course of anti-PD-1 therapy in patients with recurrent or metastatic head and neck squamous cell carcinoma (R/M HNSCC)." (PMID 36443704, 2022). "In head and neck squamous cell carcinoma (HNSCC), EGFR was found to be in a mutually interactive protein–protein complex with CaCC (ANO1/TMEM16A)." (PMID 35681682, 2022). "Cetuximab is an EGFR inhibitor that is used in the treatment of head and neck squamous cell carcinoma (HNSCC)." (PMID 35672745, 2022). "Additionally, it is well documented that TMEM16A exerts a regulative impact on the hyperplasia of cancer cells by interacting with EGFR in head and neck squamous cell carcinoma (HNSCC), an epithelial growth factor receptor in head and neck squamous cell carcinoma respectively." (PMID 33681289, 2021). "Our previous preclinical trial in a head and neck squamous cell carcinoma (HNSCC) xenograft model showed a high potential for the improvement of curative treatment outcome upon the combination treatment of a radiolabeled (Yttrium-90) anti-EGFR antibody (Cetuximab) and external radiotherapy." (PMID 34830750, 2021). "In head and neck squamous cell carcinoma (HNSCC), suppressing C1GalT1 expression by siRNA shortened the EGFR O-linked sugar chains and decreased the affinity of EGF binding to EGFR." (PMID 34944925, 2021). "EGFR is a member of the family of tyrosine kinase receptors that is overexpressed in more than 90% of head and neck squamous cell carcinomas (HNSCC)." (PMID 34262802, 2021). "Head and neck squamous cell carcinoma (HNSCC) includes a group of aggressive malignancies characterized by the overexpression of the epidermal growth factor receptor (EGFR) in 90% of cases." (PMID 34359721, 2021). "EGFR overexpression has been reported in up to 90% of human head and neck squamous cell carcinomas (HNSCC) and also in feline oral squamous cell carcinoma (OSCC), making it an interesting therapeutic target in both species 39-41." (PMID 33664868, 2021). "Important progress in the treatment of head and neck squamous cell carcinoma (HNSCC) has been made with the discovery of anti-EGFR and anti-PD-L1 therapy and their implementation into treatment protocols." (PMID 34503117, 2021). "The epidermal growth factor receptor (EGFR) is pivotal for growth of epithelial cells and is overexpressed in several epithelial cancers like head and neck squamous cell carcinoma (HNSCC)." (PMID 32054454, 2020). "In head and neck squamous cell carcinoma (HNSCC) tumors that over-expresses huEGFR, the anti-EGFR antibody, cetuximab, antagonizes tumor cell viability and sensitizes to radiation therapy." (PMID 33281820, 2020).